SDF2 (stromal cell derived factor 2)
Tractability: Antibody: UniProt places it where antibodies can reach, with high confidence; UniProt predicts a signal peptide or a membrane-spanning region. PROTAC: ubiquitination databases record sites on it; its protein half-life has been measured.
Gene: Protein-coding gene on chromosome 17 (28,648,346 to 28,662,189, reverse strand). Ensembl gene ENSG00000132581.
Subcellular location: Secreted
Subcellular location (Human Protein Atlas): Vesicles
Gene Ontology:
Molecular function: misfolded protein binding
Biological process: protein refolding
Cellular component: endoplasmic reticulum; protein folding chaperone complex
Genetic constraint (gnomAD): Loss-of-function variants: 12 observed, 21.51 expected, observed/expected ratio (o/e) 0.56, 90% interval 0.36 to 0.9. The upper end of that interval is the gene's LOEUF score, 0.9, which puts it in group 3 of 6, group 1 being the genes least tolerant of losing a copy. Missense variants: 238 observed, 278.61 expected, observed/expected ratio (o/e) 0.85, 90% interval 0.77 to 0.95. Synonymous variants: 100 observed, 108.19 expected, observed/expected ratio (o/e) 0.92, 90% interval 0.79 to 1.09.
Homologues: Orthologues: macaque SDF2 (99% identical), guinea pig SDF2 (96% identical), pig SDF2 (96% identical), mouse Sdf2 (95% identical), rat Sdf2 (95% identical), rabbit SDF2 (94% identical), dog SDF2 (79% identical), tropical clawed frog sdf2 (73% identical), zebrafish sdf2 (67% identical), Caenorhabditis elegans R12E2.13 (47% identical). Paralogues in human: SDF2L1 (64% identical), POMT2 (33% identical), POMT1 (29% identical).
Diseases named in the same sentence as SDF2 in open-access papers:
SDF2 is named in the same sentence as 9 diseases in open-access papers, as found by Europe PMC text mining. Sharing a sentence is not in itself a finding about the gene and the disease. The quoted sentences say what the papers report.
breast cancer (2 papers, 2015 to 2019). A primary or metastatic malignant neoplasm involving the breast. "Reciprocally, we isolated MRX7A, SDF2, TFPI2 and TIMP1 specifically from H1299RASSF1A ECM which, conversely to above, are positively correlated with overall survival in lung adenocarcinoma or breast cancer patients (Fig EV2A)." (PMID 31268606, 2019). "Sdf4 is a member of the stromal cell derived factor (SDFs) family and functionally classified as a chemokine; SDF-2, SDF-4 and SDF-5 are expressed in mammary tumor tissues and cells and a reduced level of SDF-2, SDF2-L1 and SDF-4 are associated with a poor clinical outcome." (PMID 26681200, 2015).
cystic kidney disease (1 paper, 2012). A congenital or acquired kidney disorder characterized by the presence of renal cysts. "Analyses indicated 13 genes, in addition to Nek8 and Ift20 within this area that could potentially result in cystic kidney disease, namely: RGD1309077Phf12, Flot2, Spag5, Sdf2, Supt6h, Proca1, Traf4, Sarm1, Nlk and Ksr1." (PMID 22899815, 2012).
Insulin resistance (1 paper, 2025). Increased resistance towards insulin, that is, diminished effectiveness of insulin in reducing blood glucose levels. "The ASE of SDF2, observed at 70:30 in the hypothalamus and 63:37 in the hippocampus in our study, along with its identification as a pig brain eQTL, suggests it may help mitigate ER stress, preserve leptin signaling, and reduce inflammation and insulin resistance." (PMID 40969342, 2025).
preeclampsia (1 paper, 2021). Preeclampsia is a hypertensive disorder of pregnancy that is characterized by new-onset hypertension with proteinuria presenting after 20 weeks of gestation, and depending on mild or severe forms may initially present with severe headache, visual disturbances, and hyperreflexia. "In addition, recent evidence shows the activation of the PERK branch correlated to SDF2 expression in cell lines and placental tissues in disorders such as severe preeclampsia." (PMID 35185601, 2021).
cardiovascular diseases (1 paper, 2024). "Additionally, SDF-2 can enhance nitric oxide (NO) release by interacting with endothelial nitric oxide synthase (eNOS), reducing the incidence of several cardiovascular diseases." (PMID 39655344, 2024).
tumor (1 paper, 2015). "Importantly, number of genes responsible tumor immune responses and desmoplastic reaction; Mst1r, TGFβr1, TGFβr2, VEGFa, CSF-1, SDF-2, CD44, IL-6ra, PD1, CD68, CD163, fibronection and MMPs were significantly reduced." (PMID 26429877, 2015).
SDF2 also shares sentences with these, for which no sentence is quoted: breast tumor (1 paper); COVID-19 (1); lung adenocarcinoma (1).